CASP8 (caspase 8)
Diseases named in the same sentence as CASP8 in open-access papers (continued):
Sharing a sentence is not in itself a finding about the gene and the disease.
temporal lobe epilepsy (1 paper, 2022). A localization-related (focal) form of epilepsy characterized by recurrent seizures that arise from foci within the temporal lobe, most commonly from its mesial aspect. "In temporal lobe epilepsy, the extrinsic apoptotic pathway predominates since caspase-8 activation precedes mitochondrial dysfunction and caspase-9 activation." (PMID 36293411, 2022).
thymic benign tumors (1 paper, 2024). "There was a causal relationship between caspase 8 levels and thymic benign tumors, a protective factor (IWV, p = 0.048, OR = 0.303, 95% CI: 0.093–0.989)." (PMID 38828408, 2024). "Caspase 8 levels, C-C motif chemokine 28 levels, interleukin-12 subunit beta levels, latency-associated peptide transforming growth factor beta 1 levels, and programmed cell death 1 ligand 1 expression showed a causal relationship with thymic benign tumors, which are protective factors." (PMID 38828408, 2024). "Caspase 8 levels, C-C motif chemokine 28 levels, IL-12 subunit beta levels, latency-associated peptide transforming growth factor beta 1 levels, and programmed cell death 1 ligand 1 levels showed a causal relationship with thymic benign tumors, which were protective factors." (PMID 38828408, 2024).
Ureteral obstruction (1 paper, 2019). Obstruction of the flow of urine through the ureter. "Cleaved caspase-8 expression increased in neonatal kidneys following ureteral obstruction." (PMID 31846485, 2019).
uterine sarcoma (1 paper, 2014). "In order to identify the cause of TRAIL resistance in the investigated uterine sarcoma cells, we investigated TRAIL receptor and caspase-8 expression at the mRNA and protein level." (PMID 24618889, 2014). "In order to compare the effectiveness of the previously published single SAHA treatment to apoptosis induction by SAHA/TRAIL or single TRAIL treatment, we monitored the activation of effector caspases-3, -6, and -7, as well as the the initiator caspase-8 in uterine sarcoma cells." (PMID 24618889, 2014). "To further confirm our hypothesis that resistance of TRAIL-mediated apoptosis may be due to promoter methylation, we monitored activation of caspase-8 and executioner caspases (caspases-3, -6, and -7) in uterine sarcoma cells which were treated for 5 days with 5-Aza-dC." (PMID 24618889, 2014).
uveal melanoma (1 paper, 2013). A melanoma derived from melanocytes of the uveal tract. "Zeaxanthin at 10–100 μM did not affect caspase-8 activities of uveal melanoma cells." (PMID 24223611, 2013).
viral encephalitis (1 paper, 2024). Encephalitis resulting from viral infection. "Through this study, it was confirmed that Caspase 8 levels, Interleukin-10 levels, Interleukin-7 levels, and TNF-beta have a positive correlation on the occurrence of viral encephalitis at the genetic level." (PMID 40008261, 2024).
viral myocarditis (1 paper, 2021). Myocarditis that is caused by an infection with a viral agent. "We found three genes (CASP8, ACTG1, and CCND1) that were significantly associated with viral myocarditis." (PMID 34722003, 2021).
vitiligo (1 paper, 2022). Generalized well circumscribed patches of leukoderma that are generally distributed over symmetric body locations and is due to autoimmune destruction of melanocytes. "Further analysis of melanocytes revealed strong pyroptosis responses existed in patients with vitiligo.Results demonstrated that CASP1, CASP4, CASP6, CASP8, and GSDMD expression was significantly upregulated in melanocytes of patients with vitiligo." (PMID 35962439, 2022).
wasting syndrome (1 paper, 2025). "Interestingly, although T cell-specific Casp8 knockout mice also developed a wasting syndrome with reduced survival rates, the specific ablation of Casp8 in T cells does not result in the same mucosal-associated pathology as observed in Ripk1ΔCD4 mice." (PMID 40307618, 2025).
Wilms' tumour (1 paper, 2004). "Previously, we had demonstrated frequent RASSF1A methylation in the same tumour series and frequent CASP8 methylation in the NB and Wilms' tumour samples." (PMID 14735202, 2004). "To date, we have not identified an association between CASP8, RASSF1A and SLIT2 methylation in individual tumours, so there is little evidence of a methylator phenotype in a subset of Wilms' tumours." (PMID 14735202, 2004). "Recently, we reported frequent CASP8 (43%) and RASSF1A (56%) promoter methylation in Wilms' tumours and the present study has demonstrated that SLIT2 methylation represents a further frequent epigenetic change in Wilms' tumours." (PMID 14735202, 2004). "Although p16INK4a(CDKN2a) promoter methylation has been reported in advanced stage Wilms' tumours, this trend was not significant in our series, and to date no specific clinicopathological features have been associated with SLIT2, CASP8 and RASSF1A methylation." (PMID 14735202, 2004).
cancer (731 papers, 2003 to 2026). A tumor composed of atypical neoplastic, often pleomorphic cells that invade other tissues. "Of these, CASP8 represents a very strong a priori candidate cancer risk gene, given its long-established role as an apoptotic initiator caspase and the fact that lower CASP8 levels are associated with cancer risk." (PMID 41542517, 2026). "In summary, our study functionally interrogated the multi-cancer risk locus on chromosome band 2q33.1, providing strong evidence for cis-regulation of CASP8 via multiple functional variants as a primary causal mechanism influencing cancer risk." (PMID 41542517, 2026). "The main Caspases implicated in cancer cell death through apoptosis include Caspase-8, Caspase-9, and the executioner Caspases, specifically Caspase-3 and Caspase-7." (PMID 40490812, 2025). "The underlying mechanism of this resistance, primarily associated with a decrease in caspase-8 activation, is linked to cellular plasticity, which allows cancer cells to escape treatment through transient resistance." (PMID 41034453, 2025). "This, in turn, rendered cancer cells more susceptible to FASL (predominantly expressed by lymphoid immune cells)-induced caspase 8-mediated apoptosis." (PMID 40847419, 2025). "Caspases play a critical role in apoptosis mechanisms, and the induction of caspase-3 and caspase-8 has been associated with cancer cell death and improved therapeutic outcomes." (PMID 40430470, 2025). "The molecular mechanisms of cancer pathway included variants in the following COSMIC driver genes: CASP8 (high impact; VAF = 0.036 in HCC tumor) and ATM (moderate impact; VAF = 0.029 in HCC cell line and VAF = 0.012 in HCC tumor)." (PMID 40340757, 2025). "Most notably, the study identified contrasting selection pressure on the two DED domains of Casp8 in bats (Chiroptera) highlighting this pathway as interest for future research into cancer susceptibility and resistance in mammals." (PMID 38773187, 2024). "Among them was a previously identified multi-cancer-associated functional variant, rs3769823, colocalized with a multi-cell-type cCRE within a CASP8 alternative promoter." (PMID 39266564, 2024). "This phenomenon explains why certain types of cancer promote the expression of mutated caspase-8 and how they even derive advantages from the expression of TRAIL-Rs." (PMID 39625520, 2024). "Intriguingly, suppressing caspase-8 is associated with increased sensitivity of cancer cells to DNA-damaging compounds and, as already pointed out, CDDP is a DNA intercalating agent." (PMID 38739308, 2024). "Several studies have shown that caspase-8 is also associated with cell metastasis, angiogenesis, and other cancer-promoting effects." (PMID 38769394, 2024). "R233 and R435 are highly conserved in mammals and their point mutations are among the most common mutations of caspase-8 in cancer." (PMID 38730267, 2024). "Evasion of apoptosis is a hallmark of cancer and Caspase-8 expression is silenced in some tumors, consistent with its central role in apoptosis." (PMID 37444381, 2023). "Evasion of apoptosis is one of the key hallmarks of cancer and Caspase-8 has commonly been associated with an antitumor protective role." (PMID 37444381, 2023). "Regarding the molecular mechanisms that drive the downregulation of Caspase-8 expression in cancer and eventually also affect its functionality, several reports identified the occurrence of inactivating mutations of Caspase-8 in tumors." (PMID 37444381, 2023). "Top-scoring regulators of apoptosis, CASP8, BAX, and MCL1, indicated the mode of cell death induced by IFN-γ, and support the association of CASP8 mutations with immune evasion in TCGA pan-cancer analyses." (PMID 36669486, 2023). "EGCG-induced apoptosis of cancer cells has been linked with a substantial decrease in Bcl-2 expression, caspase-8 activation, and proteolytic cleavage of Bid in glioblastoma cells." (PMID 36836619, 2023).
cancer (continued). "The metabolite α-KG induces death receptor 6-activated caspase-8 which activates the GSDMC-dependent pyroptosis pathway in cancer cells, causing tumor necrosis." (PMID 36042287, 2022). "Inhibition of caspase-8 or its mutations elevate the levels of chromosomal aberrations and predisposes a wide variety of cancers to necroptosis." (PMID 35409093, 2022). "Further, combining the small-molecule inhibitor with cisplatin synergistically enhanced the sensitivity of caspase-8-deficient cancer cells to chemotherapeutic drugs." (PMID 36428594, 2022). "In the cholangiocarcinoma model, treatment of both SMAC-mimetic (LCL161 and DEBIO1143) and TNF sensitizes cancer cells to a low dose of gemcitabine-induced necrosome complex formation and necroptosis upon the loss of cIAPs and caspase-8 function." (PMID 36361505, 2022). "For example, caspase 8 is commonly mutated, particularly in cancers of neuroendocrine or lymphoid origin." (PMID 35401556, 2022). "In disease context, DNMT3a has been described to be overexpressed or mutated in various carcinomas and correlates with the down-regulation of caspase-8 in these same scenarios." (PMID 36112666, 2022). "Casp8 mutations are associated with increased risks of cancer, and low expression of Casp8 is closely connected with poor prognosis in patients with cancer." (PMID 33934451, 2021). "The recurrence of caspase-8 mutations at specific sites in multiple cancers, argues that these mutations contribute to malignant progression." (PMID 34362880, 2021). "One study showed that loss of CASP8 activation is a potential mechanism for cisplatin resistance in human cancer cells." (PMID 35070983, 2021). "Coincidentally, lysosome-associated cell death driven by catalytically inactive caspase-8 was recently reported in cancer cells." (PMID 34556638, 2021). "Dysregulation of caspase-8 was suggested to contribute to apoptotic escape and to associate with malignancy and metastasis of cancers." (PMID 33810241, 2021). "A large number of caspase-8 mutations have also been identified in human cancers, although the functional properties of these mutations and their role in cancer are poorly understood." (PMID 34362880, 2021). "Overall, our study provides evidence for TMD, immunological and angiogenic dormancy signals across a variety of cancer types, and highlights key associated intrinsic and extrinsic hallmarks, including CASP8/RAS dependencies, APOBEC mutagenesis and hypoxia." (PMID 34307377, 2021). "CASP8 encodes a member of caspase family and play a role in apoptosis, and some of its polymorphism have been reported as susceptibility to various cancers including CRC41–43." (PMID 34285288, 2021). "The molecular mechanism of fascaplysin-induced apoptosis is directly linked to activation of the caspase-3, caspase-8, and caspase-9 pathways, cleavage of Bid, release of cytochrome C into cytosol and downregulation of the Bcl-2 level in cancer cells." (PMID 34440090, 2021). "Several studies have suggested that Casp8 mutations in cancers lead to differences in Casp8 protein expression, with most mutations resulting in a decrease in Casp8 protein expression." (PMID 33934451, 2021). "CASP8 plays a significant role in the apoptosis pathway, and its abnormal expression is associated with tumour cell differentiation, the cancer risk, and prognosis." (PMID 34772375, 2021). "We recruited patients with both cancer and precancerous lesion fields and studied somatic mutations at CASP8 in cancer as well as adjacent leukoplakia tissues by NGS method." (PMID 32492030, 2020). "When necroptosis directly causes cancer cells to die, caspase-8-mediated necroptosis often exhibits anti-cancer effect." (PMID 33665167, 2020). "Fifteen tumors, with CASP8 mutations, were moderate/well differentiated carcinoma and clinically N0 status but had different tumor sizes (such as T1, T2, T3 and T4a)." (PMID 32492030, 2020).
cancer (continued). "We then investigated if this effect seen in CASP8-MT HNSCs was broadly applicable across other cancers carrying CASP8 mutations." (PMID 30775178, 2019). "In earlier studies, monensin induced apoptosis-associated changes in Bax, caspase-3, and caspase-8, elevated intracellular oxidative stress in several human cancer cells, or exerted effects on the intracellular trafficking and processing of endocytosis." (PMID 31380151, 2019). "It has been reported that the six-nucleotide deletion polymorphism (-652 6N del) of the CASP8 gene had effect on some cancer risk." (PMID 30057371, 2019). "CASP8 was also mutated in other cancer types, however, the numbers of such tumors are too low for meaningful analyses." (PMID 30775178, 2019). "It has been reported that polymorphic variation in CASP8 influences cancer risk, such as the variant D302H (rs1045485), the 652 6N insertion/deletion (ins/del) promoter variant (rs3834129), and the IVS12-19G/A (rs3769818)." (PMID 30057371, 2019). "In particular, the Casp8 polymorphism 652 6N del is associated with a reduced cancer risk, especially concerning CRCs, but in vivo high expression of Casp8 in CRC is associated with poor survival." (PMID 31003440, 2019). "Subsequently, in the second part, we investigated the correlation between immune signature and survival in two carcinomas having a significant number of cases with CASP8 mutations, HNSC and UCEC." (PMID 30775178, 2019). "In this in silico study, we explore the implications of CASP8 mutations that have been identified across carcinomas through large-scale genomic studies." (PMID 30775178, 2019). "This evidence and our data would be consistent with a model whereby a subtle reduction in CASP8 function leads to reduction in cancer risk, whereas missense mutations conferring an enhanced or altered function increase cancer risk." (PMID 29316957, 2018). "Loss of apoptotic signaling is a hallmark of cancer and indeed Caspase-8 expression is often lost in tumors." (PMID 30501030, 2018). "The present meta-analysis comprehensively evaluated the relationship between the CASP8 -652 6N ins/del polymorphism and cancer risk across 49 studies (33,494 cases and 36,397 controls)." (PMID 28915630, 2017). "In agreement with the four previously published meta-analyses, we found that the CASP8 -652 6N ins/del polymorphism was associated with reduced overall cancer risk." (PMID 28915630, 2017). "Our meta-analysis of the association between the CASP8 -652 6N ins/del polymorphism and cancer risk is by far the largest such meta-analysis with the greatest statistical power published thus far." (PMID 28915630, 2017). "We also found that the CASP8 -652 6N ins/del polymorphism decreased cancer risk in population-based (DD vs. II: OR=0.83, 95% CI=0.75–0.92) and hospital-based groups (DD vs. II: OR=0.61, 95% CI=0.49–0.75)." (PMID 28915630, 2017). "The present work robustly concludes that the CASP8 -652 6N ins/del polymorphism is associated with reduced overall cancer risk." (PMID 28915630, 2017). "Second, only one CASP8 genetic variant was considered, and confounding factors, such as other genetic mutations and environmental exposures, also influence cancer susceptibility." (PMID 28915630, 2017). "Extensive epidemiological studies have assessed the association between the CASP8 -652 6N ins/del polymorphism and cancer risk." (PMID 28915630, 2017).